IL1B (interleukin 1 beta)
Diseases named in the same sentence as IL1B in open-access papers (continued):
Sharing a sentence is not in itself a finding about the gene and the disease.
Sepsis (continued). "The pathogenesis of sepsis is accompanied by the overactivation of various inflammatory factors, including IL‐1β, TNF‐α, and IL‐10." (PMID 37382273, 2023). "Concluding this Step, it seems likely there are very low IL-1β levels in the circulation in COVID-19 patients, and levels are likely lower than average levels in sepsis patients." (PMID 37928695, 2023). "Recent data has indicated that maintaining a certain amount of IL-1β prevented mice from death after sepsis in the long term." (PMID 36798132, 2023). "With assay caveats in mind, IL-1β concentrations in COVID-19 appear to be far lower than levels we determined in patients with sepsis (mean 21.8 pg./mL)." (PMID 37928695, 2023). "In sepsis, inflammatory cytokines, such as interleukin‐6 (IL‐6), IL‐1β, tumour necrosis factor (TNF), and the acute phase protein, serum amyloid A1 (SAA1), are increased in serum and skeletal muscle of patients and mice." (PMID 37209006, 2023). "In sepsis-induced kidney injury, many pro-inflammatory cytokines are released, mainly IL-1β, IL-6, and TNF-α." (PMID 36737765, 2023). "We further analyzed the area under ROC curve of disease severity score (SOFA score, APACHE II score), peripheral blood AQP4, and inflammatory factors such as TNF‐α, IL‐6, and IL‐1β of sepsis along with SAE patients." (PMID 36922751, 2023). "The potential of TNF-α, IL-1β, and IL-6 as biomarkers for patients with sepsis has been proposed, and the combined test of the three has an excellent predictive value in individuals with sepsis-induced cardiomyopathy." (PMID 37650558, 2023). "At days 1 and 7 after sepsis, blocking caspase-1 resulted in reduced levels of IL-1β, monocyte chemoattractant protein-1, and TNF-α in both the bloodstream and the brain." (PMID 37891821, 2023). "Treatment with curcumin led to the regulation of protein expression of IKKβ, IκBα, p-NF-κB, TNF-α, IL-1β, and IL-18 stimulated by sepsis." (PMID 36756300, 2023). "While there is need for further study, caution should be exercised before assuming existence of a similar hidden tissue reservoir of IL-1β in sepsis like the case for CAPS." (PMID 37928695, 2023). "Some cytokines associated with inflammation, such as IL‐1β, TNF‐α, and IL‐10, have been found to play essential roles in the occurrence and development of sepsis." (PMID 37382273, 2023). "Since then, many clinical trials have informed on the pathophysiological role of IL-1β in neonatal sepsis, including in umbilical cord blood from infants with early onset sepsis, or increased plasma IL-1β and serum IL-1β in septic infants." (PMID 36769133, 2023). "IL-1β is essential for an adequate acute inflammatory response to a variety of pathogens and injuries, but its excessive overexpression leads to sepsis, septic shock, or chronic inflammation." (PMID 38054662, 2023). "Most IL-1 sepsis research and clinical investigation has focused on IL-1β, with IL-1α receiving less attention." (PMID 37928695, 2023). "COS has also been shown to reduce systemic inflammatory responses, as indicated by serum levels of TNF-α and IL-1β and damage to the liver, kidney, and lung in a mouse model of LPS-induced sepsis." (PMID 37476483, 2023). "Previous studies showed that the regulation of the production of proinflammatory cytokines IL-1β, IFN-γ, etc., during toxoplasmosis is one of the main factors that can cause the host to survive longer after induction of sepsis and infection." (PMID 37505651, 2023). "Studies have shown that the level of IL-1β in non-survivors is higher than that in survivors, indicating that the high level of IL-1β is probably related to the adverse outcome of sepsis." (PMID 38035100, 2023). "Genetic anomaly in CAPS likely affects many or all cells capable of producing IL-1β, whereas sepsis usually originates from a focal infection and far less whole-body IL-1β production is expected compared to CAPS patients." (PMID 37928695, 2023).
Sepsis (continued). "In a sepsis model, astrocyte pyroptosis increased the release of pro-inflammatory cytokines (IL-1β and IL-18), resulting in neuron damage." (PMID 37353794, 2023). "We previously showed that IL‐1β serum levels and muscular Il6 expression were reduced in septic Nlrp3 KO mice, and that these mice are protected from muscle atrophy in sepsis." (PMID 37209006, 2023). "IL-1β is a proinflammatory protein, which is essential for the pathogenesis of systemic inflammatory responses in the initial phase of sepsis." (PMID 36766707, 2023). "Previous clinical studies have reported elevated levels of NLRP3, GSDMD, IL-1β, and IL-18 in patients with sepsis." (PMID 38161332, 2023). "Another in vivo murine experiment demonstrated that PD-L1 knockdown inhibited the expression of caspase-3 to reduce GSMDE-induced IL-1β release and suppressed the activation of integrin αIIbβ3, contributing to alleviate platelet activation in sepsis." (PMID 38022612, 2023). "ALA reduced the level of NETs, pyroptosis-related proteins (Cl-caspase-1, Cl-GSDMD, ASC), and IL-1β in the lung tissue of sepsis mice." (PMID 37051243, 2023). "It activates MyD88 then NF‐κB and finally releases inflammatory cytokines including TNF‐α, interleukin‐1β (IL‐1β), and IL‐6 which play crucial roles in occurrence and development of sepsis." (PMID 38455195, 2023). "This beneficial effect correlates with other studies evidencing that IL-1β-primed MSC-derived secretory products ameliorate sepsis through macrophage M2 polarization and favor wound healing of full-thickness excisional skin wounds." (PMID 37745306, 2023). "This increase in the sepsis group is likely attributed to the activation of macrophages, including liver Kupffer cells, which produce various inflammatory mediators such as IL-1β." (PMID 38406775, 2023). "Compared to the sepsis and vehicle groups, the Ticagrelor-pretreated group had significantly decreased lung tissue levels of pro-inflammatory cytokines (IL-6, IL1B, and TNF-α)." (PMID 37675176, 2023). "As for VE-cadherin, its expression is influenced by IL1B, another crucial inflammatory mediator in sepsis, indirectly reducing VE-cadherin transcription." (PMID 38406775, 2023). "Extensive lung endothelial cell death, the release of lactate dehydrogenase (LDH) and IL-1β, and the destruction of endothelial cell barrier are important pathological mechanisms of sepsis-induced ARDS." (PMID 38035100, 2023). "In LPS‐induced mice sepsis, pretreatment of 50 mg/kg CA greatly promoted the survival rate of septic mice and reduced the serum concentrations of IL‐1β and tumor necrosis factor (TNF)‐α." (PMID 37090118, 2023). "Mature caspase-1 cleavages IL-1β and IL-18 into maturity, both of which play critical roles in the early phase of sepsis, with elevated levels exacerbating the inflammatory response." (PMID 37711629, 2023). "One day after sepsis induction, all animals presented peritonitis with bacterial infection as well as elevated C-reactive protein, haptoglobin, IL-1Ra, IL-6, and IL-1b." (PMID 38087374, 2023). "In this study, SJS can improve the 7-day survival rate of sepsis mice, inhibit the release of inflammatory cytokines IL-1β, IL-6, TNF-α, and increase the production of IL-10 in the early stage." (PMID 37062835, 2023). "Interleukin-1β (IL-1β) is an inflammatory factor that plays a crucial role in the development of tissue and organ damage during sepsis." (PMID 37745233, 2023). "In sepsis, these cytokines (IL-1α, IL-1β, IL-6, and TNFα) can be released in the blood and cross the BBB through their respective transporters." (PMID 37569277, 2023). "In sepsis, infection first causes increased secretion of core pro-inflammatory factors such as TNF-α and IL-1β." (PMID 37636994, 2023). "We found that Daph obviously protected animals from mortality, reduced the LPS-induced alveolar edema and inflammation cells infiltration in sepsis mice, and suppressed the production of pro-inflammatory factors including IL-1β, IL-18, IL-6, TNF-α and iNOS." (PMID 36998049, 2023).
Sepsis (continued). "TGF-β1 was revealed to block early cardiac depression induced by TNF-α, IL-1β, and septic serum in sepsis." (PMID 38029224, 2023). "Sustained elevation of IL-1β level was observed in the brain after initial neonatal sepsis, which would last for at least 32 days." (PMID 37834141, 2023). "On the other hand, in murine studies of the cecal ligation and puncture (CLP) sepsis model, the overexpression of miR-181b was shown to attenuate neuroinflammation through the downregulation of NF-ΚB, IL-1β, and TNFα." (PMID 37569277, 2023). "Because inhibition of the NLRP3/IL-1β pathway slowed myocardial atrophy and cardiomyopathy in sepsis, it can prevent SCM." (PMID 37996554, 2023). "We also performed ELISA to assay the expression of inflammatory cytokines, and results revealed that the concentrations of TNF‐α, IL‐1β, and IL‐6 were notably increased in the sepsis cell model (p < .001)." (PMID 37647440, 2023). "While pyroptosis is the inflammatory form of RCD, it can release IL-1β and IL-18 in the early stages to initiate the event of sepsis." (PMID 36741074, 2023). "A previous study by our group showed that IL-1β levels were increased in the hippocampus and cerebral cortex of WT septic mice 24 h after sepsis." (PMID 37153798, 2023). "The NLRP3 inflammasome, a complex responsible for IL-1β and IL-18 release and a crucial mediator of pyroptosis, became activated in platelets in a sepsis rat model and correlated with lung and renal injury." (PMID 37081895, 2023). "Sepsis is an important cause of cytokine storm, involving increased TNF, IL-1β, and IL-6 production through proinflammatory cells and sepsis pathology." (PMID 37108210, 2023). "Through the analysis of haplotypes of IL-1β, it was found that plasma level of IL-1β can affect the 90-day mortality of sepsis." (PMID 38035100, 2023). "On the contrary, miR-483-5p and miR-497-5p resulted in aggravating pulmonary disease induced by sepsis since their overexpression determined an increased production of TNFα, IL1β and IL6, thus promoting inflammation." (PMID 36012630, 2022). "While the role of this metabolite is less described, serine is required for the optimal expression of IL1β gene and the blockade of de novo serine synthesis improve survival in a model of LPS-induced sepsis." (PMID 35154105, 2022). "Several genetic variations in genes with immunological functions, such as CTL4, IL1-B, IL6, CD40, and HMGB1, have been reported to be associated with sepsis." (PMID 36714653, 2022). "Inhibiting PKM2 activation reduced IL-1β release and improved survival in septic mice while promoting PKM2 activation increased IL-1β levels and significantly reduced the host immune response in a sepsis model." (PMID 35847986, 2022). "Studies also showed that Wip1 expression was negatively correlated with neutrophil production of inflammatory cytokines, including TNF-α, IL-6 and IL-1β, in sepsis patients, which was mediated by the p38 MAPK-STAT1 and NF-kappaB pathways." (PMID 35538489, 2022). "GC is also produced endogenously in sepsis patients in whom cytokines like IL-1β, TNFα, and IL-6 induce its production from the adrenal cortex using cholesterol as a substrate to reduce inflammatory responses." (PMID 36443794, 2022). "During sepsis, proinflammatory cytokines, such as IL-1β/TNF-α, are responsible for structural alterations in the BBB." (PMID 35295600, 2022). "IL-1β is well-known to contribute to the development of sepsis and induces the production of other inflammatory mediators." (PMID 36422559, 2022). "In sepsis induced by bacterial pathogens, the inflammatory cytokines such as IL-1β, IL-6, and TNF-α function as major mediators for shock and death induction." (PMID 35892383, 2022). "Compared with those in the sepsis group, the levels of IL-6, IL-1β and TNF-α were decreased (P < 0.05), the MDA content was decreased, with the SOD and CAT activities increasing in the sepsis + DMOG group (P < 0.05)." (PMID 35576220, 2022).
Sepsis (continued). "Sepsis-exos time-dependently elevated IL-1β and IL-18, increased miR-885-5p but decreased HMBOX1 expression." (PMID 35345489, 2022). "As proof of concept, we first demonstrated the ability of AZ106 (10 μM) to prevent endothelial dysfunction in intact rat aorta in response to IL‐1β, an inflammatory mediator upregulated during sepsis." (PMID 35668576, 2022). "PAMP/DAMP induces activation of the NLRP3 inflammasome in macrophages and production of pro-inflammatory cytokine—IL-1B, thus promoting sepsis." (PMID 36032662, 2022). "As expected, such changes ultimately led to proinflammatory cytokine production during late-stage sepsis (IL-1β, IL-6, IFNγ, TNFα)." (PMID 35349828, 2022). "When we limited the analysis to those patients admitted to wards, circulating levels of all cytokines decreased from day 1 to day 5, with the only exception of IL-1β in septic shock patients and IL-18 in sepsis patients." (PMID 36189302, 2022). "Tumor necrosis factor (TNF-α) and Interleukin 1 beta (IL-1β), the most important primary pro-inflammatory mediators, are the cytokines most extensively studied in sepsis patients." (PMID 36189302, 2022). "The levels of IL-6 and IL-1B in lung tissue were significantly (p<0.05) increased in the sepsis group compared to the sham group." (PMID 35928365, 2022). "On the other hand, NLRP3/IL-1β inflammasome pathway inhibition attenuates cardiac atrophy and cardiomyopathy in sepsis." (PMID 36359339, 2022). "Inflammatory mediators such as the pro-inflammatory cytokines IL-1β, TNFα, and IFNγ, secreted during sepsis, have been shown to induce chemerin expression in adipocytes as well as other cells." (PMID 35204801, 2022). "During the pathological progress of sepsis, several inflammatory cytokines such as IL‐1β, IL‐6, TNF‐α and IFN‐γ are excessively produced." (PMID 35502484, 2022). "Several anti-IL-1β and anti-IL-6 agents have also been developed and clinical data also demonstrate their beneficial effects against sepsis." (PMID 35337084, 2022). "It frequently results in inflammation, such as sepsis, with the primary cytokines secreted being IL-1β, IL-6, and TNF-α." (PMID 35698506, 2022). "Tumor necrosis factor alpha (TNF-α), interleukin 1 beta (IL-1β), and interleukin 6 (IL-6) are important proinflammatory cytokines that are considered the main cytokines in the pathogenesis of sepsis." (PMID 35106183, 2022). "We showed that sepsis-exo treatment elevated IL-1β and IL-18, decreased HMBOX1, and promoted pyroptosis in AC16 cells." (PMID 35345489, 2022). "Blocking C1q function locally at the site of inflammation dramatically increased sepsis mortality and significantly increased the serum levels of the proinflammatory cytokines IL-6 and IL-1b in both the endotoxemia and CLP mouse sepsis models." (PMID 35983035, 2022). "The compound showed protective effect against endotoxin-induced sepsis by displaying dose-dependent suppression of LPS-induced production of IL-1β and prostaglandin E2 (PGE2) in isolated mouse peritoneal macrophages and RAW 264.7 cells." (PMID 36588685, 2022). "The overexpression of many proinflammatory cytokines, such as TNF-α, IL-1β, and IL-6, is closely related to severe sepsis." (PMID 35370629, 2022). "It proposed a classification model in which IFNγ elevations >83pg/ml or low/moderate IFNγ-elevations <83pg/ml in conjunction with low IL1β <8pg/mml were associated with CRS whereas low IFNγ and IL1β >8pg/mml were consistent with sepsis with 97% accuracy." (PMID 35402259, 2022). "During sepsis, elevated cytokines (tumor necrosis factor-alpha, interleukin-6, interleukin 1 beta) alters sympathovagal balance." (PMID 35572539, 2022). "Children with sepsis had significantly higher levels of IL-1β, IL-12 and IL-17A compared to febrile controls but lower levels of MIP1-β/CCL4, RANTES/CCL5 and IP10/CXCL10 when compared to children with malaria and febrile controls." (PMID 35811678, 2022).
Sepsis (continued). "Sepsis-exos also enhanced the secretion of IL-1β and IL-18 and decreased HMBOX1 expression in mRNA and protein levels." (PMID 35345489, 2022). "Shikonin also prevented the activation of the NLRP3/caspase-1/IL-1β inflammasome pathway and increased the survival rate of Balb/c mice with LPS-induced lethal endotoxemia and caecal ligation and puncture–induced sepsis." (PMID 35637461, 2022). "It is suggested that fisetin interacted directly with CMECs (the main component of BBB) to reduce the secretion of inflammatory factors (IL‐1β) into the CNS after sepsis, thereby attenuating central inflammation and cognitive impairment." (PMID 34837343, 2022). "We showed that sepsis-exo or miR-885-5p mimic not only elevated IL-1β and IL-18, but also increased NLRP3, caspase-1, and GSDMD-N, leading to promotion of pyroptosis." (PMID 35345489, 2022). "The serum levels of IL-6 and IL-1β were significantly elevated in C1q cKO mice compared with control mice, indicating an increased sepsis severity." (PMID 35983035, 2022). "Other studies have identified the use of IL-1β, CCL4, CCL5 and CXCL10 as possible diagnostic markers for sepsis." (PMID 35811678, 2022). "For instance, IL-1β-primed mesenchymal stem cells have been shown to dampen hyper-inflammation in murine sepsis models." (PMID 35163021, 2022). "The compound was found to suppress the overexpression of MMP-9, IL-1β, IL-6 and iNOS induced in LPS-induced sepsis mouse models and the TC-1 cell line in a dose-dependent manner." (PMID 36588685, 2022). "To further mimic the sepsis model in vivo, we stimulated HUEVCs with recombinant human IL-1β in vitro." (PMID 36278213, 2022). "Another report found that miRNA-21 was massively upregulated in exosomes released by IL-1β-stimulated MSCs, which induced macrophage polarization to M2 type and thus ameliorated sepsis." (PMID 35326456, 2022). "Bacteremia and subsequent endotoxemia directly stimulate the release of inflammatory cytokines, including TNF-α, IL-1β, IL-6, IL-12, and IL-18 in sepsis." (PMID 36120368, 2022). "When contrasting with the sepsis group, the 10 mg/kg Montelukast pre-treated group showed considerably lower expression of inflammatory markers IL-6 and IL-1B." (PMID 35928365, 2022). "The pathogen-associated molecular patterns and damage-associated molecular patterns in sepsis activate NLRP3 and caspase-1 to release inflammatory cytokines such as IL-18 and IL-1β, aggravating the inflammatory response." (PMID 36032662, 2022). "Circulating cardiac depressant factors such as tumor necrosis factor α (TNF-α), interleukin (IL)-6, IL-1β, NO, bacterial RNA and DNA, and lysozyme C have also been described in sepsis." (PMID 35706715, 2022). "We also observed that the expression of IL-1β (p17) and Caspase (p20) was increased in macrophages from Card9−/−-sepsis mice compared with WT-sepsis mice." (PMID 35618701, 2022). "The present study confirmed enhanced TNF-α, IL-1β, and miR-103a-3p expressions in sepsis-induced AKI." (PMID 35510354, 2022). "Sepsis is characterized by an overwhelming systemic proinflammatory response to infection and is partly attributable to a “cytokine storm”, such as IL-1β, IL-6, and TNF-α." (PMID 36064371, 2022). "CLP sepsis caused increased expression of the pro-inflammatory cytokines TNF-α, IL-1β, IL-6, as expected." (PMID 35625756, 2022). "During sepsis, the expression levels of proinflammatory cytokines, such as TNF, IL-6 and IL-1β, are increased in the central nervous system (CNS), which is believed to play a pivotal role in long-term cognitive impairment after sepsis." (PMID 35883093, 2022). "Meng’s group also showed that endotoxin lipopolysaccharides via TLR4 signaling pathway to activate translocation of NF-κB and further regulate expression of pro-inflammatory genes, including TNF-α, IL-6, and IL-1β during sepsis." (PMID 35370629, 2022). "In the present study, IL-1β levels remained elevated in the hippocampus, forty-five days after sepsis." (PMID 35798809, 2022).